GLS (glutaminase)
Diseases named in the same sentence as GLS in open-access papers (continued):
Sharing a sentence is not in itself a finding about the gene and the disease.
glioblastoma (continued). "Human glioblastoma multiforme (GBM) tumors display high GS and low GLS activity, and for this reason accumulate large pools of glutamine from glucose." (PMID 29463059, 2018). "Furthermore, some reports have suggested that inhibition of GLS slows down the growth of glioblastoma cells and therefore may be therapeutic strategy against such cancers." (PMID 26179909, 2015). "Studies showed that inhibition of GLS and GDH1 significantly reduced the tumorigenesis of glioblastoma cells." (PMID 39330272, 2024). "We studied the metabolic effects of inhibiting GLS activity in T98G, LN229, and U87MG human glioblastoma cell lines by using the inhibitor CB-839." (PMID 36672480, 2023). "Glutaminase inhibitor 968 functions as an allosteric GLS inhibitor and has been found to have a good effect on tumor stem cells in glioblastoma and diminished tumor growth." (PMID 37924140, 2023). "Upon entry, glutamine is converted to glutamate by glutaminase (GLS), an enzyme directly targeted by miR-153, and miR-203, frequently downregulated in glioblastoma and melanoma, respectively." (PMID 35348905, 2022). "The aim was to investigate the effect of GLS and GAB expression on both miRNAs and oxidative status in glioblastoma cells." (PMID 33610185, 2021). "Additionally, blockade of glutaminase activity with BPTES reduced viral replication, underscoring the importance of anaplerotic pathways in glioblastoma cells." (PMID 41902234, 2026). "Furthermore, four abnormally expressed metabolic enzymes that directly regulate metabolites (GLS, GDH1, HK2 and G6PD) were downregulated by Chr-A in glioblastoma cells." (PMID 39330272, 2024). "Glutaminase isoenzyme GLS is one of the responsible enzymes for the pro-oncogenic pathways that induce metabolic reprogramming and leads to altered levels of some amino acids and other key intermediary metabolites in glioblastoma." (PMID 36672480, 2023). "In this study, GLS silencing significantly decreased viability and proliferation of glioblastoma T98G cells which do not express appreciable amounts of GA isoforms arising from GLS2 gene." (PMID 24096582, 2014). "From the clinical perspective, it is to be hoped that that combination of modulation of expression and/or activity of GA isoforms arising from GLS and GLS2 gene products may in the future provide a useful treatment modality to prevent glioblastoma growth." (PMID 24096582, 2014). "Four abnormally expressed metabolic enzymes, glutaminase (GLS), glutamate dehydrogenase 1 (GDH1), hexokinase 2 (HK2) and glucose-6-phosphate dehydrogenase (G6PD), which directly affect metabolites in certain pathways, were found to be downregulated by Chr-A in glioblastoma cells." (PMID 39330272, 2024). "Interestingly, the expression of GLS is upregulated in glioblastoma compared to non-tumorigenic brain tissues, reinforcing the idea that GLS and GLS2 play opposing roles in certain cancer types." (PMID 38067269, 2023). "Here we show that pharmacological inhibition of glutaminase (GLS) eradicates glioblastoma stem-like cells (GSCs), a small cell subpopulation in glioblastoma (GBM) responsible for therapy resistance and tumor recurrence." (PMID 32337072, 2020). "In glioblastomas (WHO grade IV), the most malignant brain tumors, high levels of GLS and only traces or lack of GLS2 transcripts were found." (PMID 24096582, 2014). "An intriguing question arose whether or not combination of GLS silencing and GLS2 overexpression would increase the inhibition of cell proliferation and survival of glioblastoma cells elicited by individual manipulations." (PMID 24096582, 2014). "The results show that combination of negative modulation of GA isoforms arising from GLS gene with the introduction of the GLS2 gene product, GAB, may in the future provide a useful means to curb glioblastoma growth in situ." (PMID 24096582, 2014).
melanoma (36 papers, 2015 to 2025). A malignant, usually aggressive tumor composed of atypical, neoplastic melanocytes. "Upon ADI-PEG 20 treatment, leiomyosarcoma and melanoma cells shunted glucose-derived carbons into the serine biosynthesis pathway, leading to susceptibility to anti-folates and glutaminase inhibition." (PMID 40813699, 2025). "Using pharmacological agents, including dabrafenib (BRAFi), pimasertib (MEKi), dasatinib (cKITi), and CB-839 (glutaminase inhibitor), we explored metabolic adaptations in melanoma cell lines harboring various mutations." (PMID 40943167, 2025). "In temozolomide (TMZ)-resistant melanoma cells, both Gln metabolism and GLS expression are upregulated, and overexpression of miR-203, which targets GLS, can reverse TMZ resistance." (PMID 40539068, 2025). "For example, a study on the long noncoding RNA OIP5-AS1 found that OIP5-AS1 increases GLS expression and is correlated with shorter survival in melanoma patients." (PMID 40943167, 2025). "We demonstrate that glutaminase 1 (GLS1) expression is specifically upregulated in CDK4/6i-induced senescent BrafV600E melanoma cells." (PMID 39695080, 2024). "Discussion: This finding opens up new therapeutic strategies based on metabolic inhibitors of glutaminase and fatty acid oxidation for the treatment of CTCs and melanoma metastases." (PMID 39175551, 2024). "Here we observed an importance for amino acid metabolism, specifically showing that both GLS expression and functional glutaminolysis dependence were significantly reduced in melanoma patients, with a progressive decrease in worse outcome group DC." (PMID 37938561, 2023). "For example, lncRNA OIP5-AS1 can upregulate GLS mRNA expression level in melanoma cells by competitively sponge with GLS-binding miR-217 and reduced the inhibitory effect of miR-217-on GLS." (PMID 37127605, 2023). "To further explore this, we tested if glutaminase inhibition depleted TCA cycle intermediates to a greater extent in the G6PD mutant as compared to control melanomas." (PMID 35110412, 2022). "Both GSH and Trolox partially rescued the much more profound effects of glutaminase inhibitor on the growth of G6PD mutant melanoma cells." (PMID 35110412, 2022). "Glutaminase inhibition thus increased ROS levels to a greater extent in G6PD mutant as compared to control melanoma cells." (PMID 35110412, 2022). "Glutaminase inhibition typically reduced GSH/GSSG ratios to a greater extent in the G6PD mutant as compared to control melanoma cells." (PMID 35110412, 2022). "G6PD mutant melanoma cells were therefore far more sensitive to glutaminase inhibition than control melanoma cells." (PMID 35110412, 2022). "This generated a new metabolic vulnerability as G6PD mutant melanomas were more dependent upon glutaminase than control melanomas, both for oxidative stress management and anaplerosis." (PMID 35110412, 2022). "MTF is a pro-tumoral gene promoting the proliferation of melanoma cells, and GLS is one of the differentiated expressed genes of MTF silencing tumors." (PMID 36003780, 2022). "To test if glutaminase inhibition increased oxidative stress in G6PD mutant melanoma cells, we measured ROS levels (CellRox green) and GSH to GSSG ratios in G6PD mutant and control melanoma cells treated in culture with 100 nM CB-839 or vehicle control." (PMID 35110412, 2022). "Additional studies are also needed to further characterize the effects of glutaminase inhibition in melanoma, including further characterization of metabolic effects and the impact on MBMs with relatively Low OXPHOS." (PMID 33575655, 2021). "In order to assess a role for glutamine metabolism in metabolic reprogramming following CDK4/6 inhibition in melanoma, we first assessed the levels and activity of a key enzyme involved in glutamine metabolism, glutaminase (GLS1)." (PMID 33572972, 2021). "In fact, BRAF-inhibitors-resistant melanoma cells increase uptake of glutamine and show overexpression of glutaminase (GLS)." (PMID 34073463, 2021).
melanoma (continued). "When analyzing melanoma tissues, miR-137 expression was found to be decreased, while GLS was overexpressed in relation to the adjacent normal tissues." (PMID 32326003, 2020). "Recent study found that the expression of GLS is up-regulated and correlates with pathological factors in leukemia, glioma, melanoma, as well as in pancreas, bladder, lung, and breast cancers." (PMID 31196962, 2019). "In those studies, melanoma cells with acquired resistance to BRAFV600E or MEK inhibitors depended on glutamine metabolism for survival and were susceptible to glutaminase inhibition." (PMID 31461993, 2019). "ADI-PEG20 and glutamine metabolism inhibition by BPTES and silencing GLS expression induced synthetic lethality and significantly reduced tumor growth in melanoma xenograft in vivo." (PMID 28750681, 2017). "Moreover, therapeutic targeting of the oxidative phosphorylation pathway with IACS-10759 or of glutamine metabolism with glutaminase inhibitor CB839 in mouse models of melanoma BrM improved survival and reduced BrM burden." (PMID 40355907, 2025). "Importantly, targeting key enzymes within this pathway, for example, glutaminase inhibition, has been shown to reduce melanin production and suppress melanoma progression, underscoring its dual role in pigment regulation and tumor biology." (PMID 41468441, 2025). "Similarly, lncRNA OIP5-AS1 is upregulated in melanoma by sponge miR-217, which leads to increased GLS expression and promotion of glutamine catabolism and melanoma growth." (PMID 37384249, 2023). "However, the expression of PDHA1, PDHB, and GLS was significantly higher in melanoma than in normal tissues." (PMID 36824136, 2023). "Our group has established that GLS overexpression, in mGluR1-expressing melanoma cell lines transpires at least in part through the mTORC/c-Myc axis as seen through the steady knockdown of c-Myc with reduced mTOR phosphorylation and the subsequent downregulation of GLS (unpublished results)." (PMID 36139432, 2022). "For example, miR-605-5p was markedly downregulated in melanoma tissues and cells and inhibited melanoma progression and glutamine catabolism through targeting GLS; miR-876-3p functioned as a tumor suppressor and correlated with cell metastasis in pancreatic adenocarcinoma via targeting JAG2." (PMID 33363164, 2020). "In addition, miRNA-137 inhibits growth of malignant melanoma by targeting GLS." (PMID 33610185, 2021). "Therefore, in this study, we hypothesize that melanoma cells resistant to RTKi/MAPKi undergo a metabolic switch toward glutaminolysis, and that this dependency can be therapeutically targeted using the glutaminase inhibitor CB-839 to overcome resistance and restore antitumor efficacy." (PMID 40943167, 2025). "Oxidative stress thus appears to have contributed to the effects of glutaminase inhibition on the growth of G6PD mutant and control melanoma cells." (PMID 35110412, 2022). "To test if antioxidants would rescue the effect of glutaminase inhibition on the growth of G6PD mutant and control melanomas, we treated A375 cells with a low concentration of CB-839 (1 nM)." (PMID 35110412, 2022). "TMZ has been combined with inhibitors that target not only MGMT, NF-κB, and Notch signaling but also AKT, mTOR signaling, autophagy, and glutaminase-mediated glutamine metabolism, all of which significantly enhanced TMZ cytotoxicity in melanoma cells." (PMID 32899791, 2020). "The effect of targeted therapeutics on the expression of glutaminase and glutamine transporters in drug-sensitive, patient-derived melanoma cells have not been described before." (PMID 31461993, 2019). "Preliminary studies conducted in melanoma cells by our group have shown that the knockdown of c-Myc via shRNA did not lead to a parallel downregulation of GLS expression, suggesting that a concomitant decrease in mTORC may be essential." (PMID 36139432, 2022).
melanoma (continued). "CRGs with low and moderate CNV, such as PDHA1, DLAT, GLS, and LIAS, were overexpressed in CRC comparison to those in normal melanoma samples, whereas CRGs with high CNV, such as PDHB, were significantly increased in melanoma samples, implying that CNV may regulate CRG mRNA expression." (PMID 36824136, 2023).
colon carcinoma (31 papers, 2015 to 2025). "High expression of YTHDF1 in human colon tumour cells causes cisplatin resistance through the enhancement of glutaminase synthesis, and inhibition of glutaminase synergizes with the tumour-suppressing effect of cisplatin." (PMID 36859310, 2023). "Collectively, these results corroborate that glutaminase inhibition synergizes with Palbociclib to impair colon cancer cell proliferation in vitro." (PMID 40696167, 2025). "Hypoxia induces high expression of glutaminase 1 (GLS1), the hydrolysis enzyme of Gln, in colon cancer cells, which promotes colon cancer cell migration and tumor growth." (PMID 39465140, 2024). "It has been found that YTHDF1 can promote glutaminase (GLS) protein synthesis in colon tumors and highly expressed YTHDF1 can lead to the development of drug resistance." (PMID 39033180, 2024). "Curcumin also upregulated miR-137 to inhibit the mRNA expression of glutaminase, which was overexpressed in cisplatin-resistant HT-29 colon cancer cells." (PMID 39061884, 2024). "Whilst the read-outs of epitranscriptome marks such as m6A-methylation are very diverse, epitranscriptomic and mRNA translation control of GLS is supported by YTHDF1-dependent GLS regulation in colon cancer." (PMID 39313128, 2024). "This is consistent with previous findings where curcumol and the combination of curcumin and cisplatin attenuated glutaminase activity in hepatic stellate cells and colon cancer cells." (PMID 38992159, 2024). "Consistent with previous studies, our work confirmed that GLS expression was upregulated in colon tumor tissues, and GLS copy number gain was greater than copy number loss." (PMID 37072493, 2023). "YTHDF1 was highly expressed in cisplatin-resistant colon cancer cells and increased the translation of glutaminase 1 (GLS1) to enhance colon cancer cell proliferation." (PMID 36835633, 2023). "In this regard, the enzyme glutaminase (GLS1), which catalyzes the first step of glutamine metabolism, is highly expressed in colon cancer and linked to significantly reduced survival." (PMID 34572981, 2021). "In colon cancer, by interacting with the CFIm complex with allele specific affinities, lncRNA CCAT2 rs6983267 regulates the alternative splicing of glutaminase, resulting in reprogramming of cancer metabolism." (PMID 34336850, 2021). "Herein, we have approached this by analyzing transcriptomic and metabolomic responses elicited in colon cancer cells that persist after exposure either to the CDK4/6i Palbociclib or the glutaminase inhibitor Telaglenastat (CB-839), or their combination, in vitro and in vivo." (PMID 40696167, 2025). "Furthermore, glutaminase is induced by hypoxia-inducible factor 1α in colon cancer cells and plays a pro-metastatic role in colon cancer metastasis." (PMID 35847893, 2022). "Therefore, to further confirm the involvement of the EZH2-GLS axis in the adaptation to glucose deprivation, we performed immunofluorescence staining for EZH2 and GLS in larger colon cancer tissues." (PMID 34671029, 2021). "Silencing of glutaminase via promoter hypermethylation has been demonstrated in colon cancer." (PMID 30498570, 2018). "The research found that the inhibition of SIRT4 would activate GLS, thereby initiating AKT activation, suggesting that GLS might influence the proliferation, migration, and invasion of colon cancer cells through the AKT/GSK3β/CyclinD1 pathway under the regulation of SIRT4." (PMID 41152153, 2025). "Targeting YTHDF1 can regulate glutaminase (GLS)-mediated glutamine metabolism, re-sensitizing cisplatin-resistant colon cancer cells." (PMID 40483535, 2025). "Three of the eight colonic tumor-related genes, ABCA1, PLA2G7, and SCARB1, were significantly correlated with GLS, the main enzyme for glutamate metabolism." (PMID 36843944, 2023).
colon carcinoma (continued). "Additionally, through immunohistochemical staining analysis of paraffin sections from COAD patients, we discovered that the expression levels of GLS and YAP1 proteins in colon cancer tissues were also significantly upregulated." (PMID 41152153, 2025). "Moreover, CB-839, the specific glutaminase (GLS1) inhibitor, was reported to improve the efficacy of anti-PD-1 or anti-PD-L1 antibody in a mouse CT26 colon carcinoma model." (PMID 38791327, 2024).